CHCHD2P9 (coiled-coil-helix-coiled-coil-helix domain containing 2 pseudogene 9)
Synonyms: formerly C9orf49; CHCHD9
Gene: Processed pseudogene on chromosome 9 (79,391,304 to 79,391,759, forward strand). Ensembl gene ENSG00000186940.
Subcellular location: Mitochondrion
Diseases named in the same sentence as CHCHD2P9 in open-access papers:
CHCHD2P9 is named in the same sentence as 6 diseases in open-access papers, as found by Europe PMC text mining. Sharing a sentence is not in itself a finding about the gene and the disease. The quoted sentences say what the papers report.
glioma (1 paper, 2025). A benign or malignant brain and spinal cord tumor that arises from glial cells (astrocytes, oligodendrocytes, ependymal cells). "Our investigation into the biological functions of CHCHD2P9, a mitochondrial-associated protein, further elucidated its role in glioma cell growth dynamics and motility." (PMID 40630954, 2025). "In conclusion, our study provides compelling evidence that CHCHD2P9 plays a crucial role in regulating glioma cell growth, motility, and survival, with significant implications for glioma pathogenesis." (PMID 40630954, 2025). "While the role of CHCHD2 and related proteins in tumorigenesis has been more clearly elucidated, the functional contribution of CHCHD2P9 in glioma remains poorly understood." (PMID 40630954, 2025). "The involvement of CHCHD2P9 in mitochondrial processes positions it as a potential therapeutic target for gliomas, particularly in the context of targeting mitochondrial dysregulation." (PMID 40630954, 2025). "CHCHD2P9 is significantly overexpressed in glioma patients, and its differential expression plays a crucial role in regulating glioma cell proliferation and migration." (PMID 40630954, 2025). "The elevated expression of CHCHD2P9 within this cellular subset suggests its potential role in regulating glioma cell differentiation, lineage commitment, and the maintenance of tumor aggressiveness." (PMID 40630954, 2025). "Parallel experiments conducted in LN229 cells yielded similar results, suggesting that CHCHD2P9 influences glioma cell migration across different cellular contexts." (PMID 40630954, 2025). "Computational analysis identified distinct expression patterns of CHCHD2P9 across different glioma subtypes, challenging its conventional annotation as a non-functional pseudogene." (PMID 40630954, 2025). "In conclusion, our study identifies CHCHD2P9 as a key mitochondrial-related protein involved in glioma progression." (PMID 40630954, 2025). "Given its putative mitochondrial association and sequence homology, CHCHD2P9 warrants further investigation as a potentially novel regulatory molecule in glioma biology, although current evidence does not yet support its classification as a bona fide mitochondrial protein." (PMID 40630954, 2025).
CHCHD2P9 also shares sentences with these, for which no sentence is quoted: asthma (2 papers); glioblastoma (1); Obesity (1); tumor (1); type 2 diabetes (1).